LAMP1 (lysosome associated membrane protein 1)
Diseases named in the same sentence as LAMP1 in open-access papers (continued):
Sharing a sentence is not in itself a finding about the gene and the disease.
lung carcinoma (11 papers, 2013 to 2024). "The correlation analysis also demonstrated that there was a positive correlation between hsa_circ_0030998 expression and LAMP1 expression in lung cancer (r = 0.6529, P < 0.0001)." (PMID 33190405, 2021). "When BMPR2 activity was inhibited with JL5, Ym155, or siRNA knockdown of BMPR2, lysosomal activity was increased in lung cancer cells as demonstrated by an increase in lysosome acidification, LAMP1 expression, and Cathepsin B activity." (PMID 34563224, 2021). "Based on the data from the Kaplan–Meier plotter, we also discovered that the high expression of LAMP1 also displayed a long survival rate of lung cancer patients." (PMID 33190405, 2021). "We confirmed that DRAM1 mainly localized to lysosomes (mCherry-LAMP1 positive), and later endosomes (GFP-RAB7 positive and GFP-RAB9 positive) in lung cancer cell." (PMID 32943616, 2020). "We also observed a similar differential expression of LAMP1 and EGFR in eight patient lung cancers that harbored mutant versus two EGFR WT." (PMID 32194831, 2020). "To determine whether lung cancer cells with induced TMEM106B expression show increased lysosomal exocytosis, we co-expressed RFP-tagged LAMP1 in the cells expressing GFP-tagged TMEM106B or GFP as control." (PMID 30013069, 2018). "Notably, LAMP1 was significantly downregulated in renal cancers, including Kidney Renal Clear Cell Carcinoma (KIRC), Kidney Chromophobe (KICH) and Kidney Renal Papillary Cell Carcinoma (KIRP), as well as lung cancers such as lung adenocarcinoma (LUAD) and lung squamous cell carcinoma (LUSC)." (PMID 39669571, 2024).
Sepsis (11 papers, 2013 to 2025). Sepsis is defined as life-threatening organ dysfunction caused by a dysregulated host response to infection. "Specifically, we have assessed various urinary biomarkers at different stages of sepsis development and identified lysosome-associated membrane protein-1 (LAMP-1) as being closely related to a poorer prognosis, which revealed the important role of autophagy during the progression of sepsis." (PMID 30952998, 2019). "In sepsis pathogenesis, ZKSCAN3 up-regulation suppresses LC3-II and LAMP1 expression, compromising lysosomal activity and pathogen clearance capacity." (PMID 40723888, 2025). "For instance, the first host response gene expression assay for diagnosis of sepsis, SeptiCyte LAB, is based on the four marker genes CEACAM4, LAMP1, PLAC8 and PLA2G7." (PMID 34555028, 2021). "Recently, many genes have also been identified for sepsis diagnosis and prognosis; for example, SeptiCyte Lab combined with CEACAM4, LAMP1, PLA2G7, and PLAC8 genes was identified to determine which patients had sepsis." (PMID 32922168, 2020). "Notably, secondary death in sepsis survivors is mostly triggered by pulmonary infection and respiratory failure, and abnormalities in autophagy markers (e.g., LC3-II, LAMP1) suggest that lysosomal dysfunction may be a key component of immunosuppression." (PMID 40723888, 2025). "In addition, the cathepsin Z was translocated from the bile canaliculus region of hepatocytes to the cytoplasm, particular in sepsis and Alagille syndrome and immunofluorescence staining showed that cathepsin Z was no longer colocalized with LAMP1 in all three diseases." (PMID 30087368, 2018).
hepatocellular carcinoma (10 papers, 2017 to 2025). A malignant tumor that arises from hepatocytes. "CTRP3 was found to interact with the lysosomal-associated membrane protein 1 (LAMP1) in rat H4IIE hepatoma cells." (PMID 36831095, 2023). "In line with this, we observed partial co-localization with the lysosomal marker LAMP1 in PID1-knockdown hepatoma cells." (PMID 30100244, 2018). "It has been reported that CTRP3 binds to the lysosomal proteins, LAMP1 and LIMP II in a hepatoma cell line." (PMID 31615574, 2019).
malaria (10 papers, 2016 to 2024). Malaria is a serious and sometimes fatal disease caused by a parasite that commonly infects a certain type of mosquito which feeds on humans. "When PBMCs from malaria-naïve individuals are incubated with iRBCs, NK cells have been shown to increase expression of the cytotoxic molecules perforin, granzyme A, and CD107a (LAMP-1)." (PMID 31533835, 2019). "As a result, all parasite-containing autolysosomes were both LC3- and LAMP1-positive, but none were stained with Cathepsin D, indicating that the malaria parasite inhibits autolysosome maturation." (PMID 27901110, 2016).
prostate carcinoma (10 papers, 2014 to 2026). A carcinoma that arises from epithelial cells of the prostate gland. "Mechanistically, AGG stimulates cytoplasmic SIRT1 that in turn, deacetylases LAMP1 (lysosomal associated membrane protein 1) on lysine residues of the cytosolic domain, resulting in lipophagy-mediated senescence in prostate cancer cells." (PMID 35317831, 2022). "This rapid and increasing uptake underscores the potential of LAMP1-based radiopharmaceuticals for imaging and therapeutic applications across a spectrum of human carcinomas, such as colon, breast, and prostate cancers." (PMID 40872517, 2025). "Silencing LAMP1 using siRNA significantly inhibits the proliferation, migration, and invasion of prostate cancer cells." (PMID 39669571, 2024). "It becomes evident that LAMP1 not only serves as a downstream target for miR-320a but also influences prostate cancer progression through modulation cell-autonomous mechanisms governing cellular self-degradation processes such as autophag." (PMID 39669571, 2024). "Deacetylation process targeting LAMP1 promotes AGG-induced lipolysis-dependent generation FFAs thereby promoting senescence specifically in prostate cancer." (PMID 39669571, 2024). "Overexpression of LAMP1 was observed in clinical specimens of prostate cancer and metastatic prostate cancer." (PMID 39669571, 2024). "Moreover, high expression levels of LAMP1 in the plasma membrane were observed, inter alia, in colorectal neoplasm tissues, advanced prostate cancer (PCa), and castration-resistant prostate cancer (CRPC)." (PMID 32993062, 2020). "We also demonstrated the potential applicability of LAMP1-based PET for a variety of carcinomas by performing LAMP1 immunofluorescence staining on human colon, breast, and prostate carcinoma samples, as well as genomic analysis." (PMID 40872517, 2025). "22Rv1 prostate cancer cells and PNT1a non-malignant prostate cells transiently expressing, respectively, Lamp1-GFP and -RFP were co-cultured and imaged." (PMID 39858418, 2024). "Here, we have investigated the spatiotemporal dynamics of lysosomes, using live-cell imaging of lysosomal associated membrane protein 1 (LAMP1)-GFP-transfected non-malignant prostate epithelial cell lines (PNT1a, PNT2 and PWR1E) and prostate cancer cell lines (22Rv1, LNCaP, DU145, and PC-3)." (PMID 39217195, 2024).
colorectal cancer (9 papers, 2016 to 2024). A primary or metastatic malignant neoplasm that affects the colon or rectum. "Indeed, ABCB1 colocalizes with lysosomal-associated membrane protein 1 (LAMP1) in human colorectal cancer HTC15 cells." (PMID 33672718, 2021). "In colorectal cancer epithelium, LAMP1 and LAMP2 levels are increased, suggesting that LAMPs are related to neoplastic progression, but there is no direct association between such up-regulated expression and cell proliferation." (PMID 27627761, 2016). "Indeed, expression of the lysosomal/late endosomal marker LAMP1 correlates with low ROS levels in CSCs in colorectal cancer." (PMID 35216401, 2022). "Furthermore, the inhibition of lysosomal functions by mefloquine reduces the levels of LAMP1/2 as well as the early and late endosome markers Rab5 and Rab7, respectively, leading to the elimination of CSCs via dysfunctional mitochondrial clearance in a colorectal cancer model." (PMID 35216401, 2022).
Obesity (9 papers, 2016 to 2026). Accumulation of substantial excess body fat. "Interestingly, obesity induced by a high fat-diet or Bif-1 deficiency downregulates the expression of proteins involved in the autophagy-lysosomal pathway, including Atg9a and Lamp1 in the adipose tissue." (PMID 26857140, 2016). "Compared to controls, immune‐related pathways such as adaptive immunity and leukocyte‐mediated processes (e.g., STX7, HPX, LAMP1, C5) were upregulated in obesity." (PMID 41077621, 2026). "To explore the potential importance of the mTOR/TFEB/LAMP1 axis in NK cells isolated from individuals W/O or WO/O obesity, we performed RT-qPCR analysis and Western blotting analysis." (PMID 39718832, 2024). "The increase in surface LAMP-1 in CLS macrophages suggests that macrophage lysosome exocytosis is occurring in vivo in a mouse model of obesity." (PMID 27044658, 2016). "To determine if a loss in lysosomes was also present in NK cells of individuals W/O, we performed RT-qPCR analysis and found that LAMP1 mRNA expression was 45.8% ± 3% reduced when compared with individuals WO/O, highlighting the similarities between hyperlipidemia and obesity in NK cells." (PMID 39718832, 2024). "As the downregulation of Atg9 and Lamp1 in Bif-1 KO adipose tissue was only observed in 30-week-old but not 6-week- or 10-week-old animals, this effect appears to be a consequence of the development of obesity in Bif-1 KO mice." (PMID 26857140, 2016). "Therefore obesity-attributed hyperinsulinemia in Bif-1 KO mice may mediate the downregulation of Atg9 and Lamp1 through the activation of mTOR and suppression of TFEB signaling, and this hypothesis warrants further investigation in the future." (PMID 26857140, 2016). "A main effect of obesity on LC3 was found along with reduced LAMP1 in males with no changes in p‐mTOR Ser4228." (PMID 40677154, 2025).
Stroke (9 papers, 2018 to 2025). Sudden impairment of blood flow to a part of the brain due to occlusion or rupture of an artery to the brain. "Autophagy-associated proteins, such as Catsl and Lamp1, were upregulated in B cells from stroke mice." (PMID 39195931, 2024). "Remarkably, proteins associated with neutrophil degranulation (Lamp1, S100a8 and CD47) and neutrophil activation (Il1r2 and Stat3) were upregulated in stroke mice." (PMID 39195931, 2024). "Additionally, XXMD/CsA downregulated LC3B, Beclin1, and Lamp1 expression and reduced p62 translocation to mitochondria, which may be related to attenuated mitochondrial dysfunction and suppressed mitophagy after stroke." (PMID 30018669, 2018). "Increased levels of granulin A were detected in microglia after stroke, and granulin-A signals overlapped with signals detected by the commercial anti-PGRN antibodies and anti-LAMP1 antibodies, indicating increased levels of lysosomal granulin-A upon microglial activation in response to stroke." (PMID 35120524, 2022). "EE was shown to increase the expression of LAMP-1 protein in animal models of chronic cerebral hypoperfusion, vascular occlusion, and stroke Additionally, EE led to a reduction in p62 protein levels under conditions of CUMS, stroke, and chronic cerebral hypoperfusion." (PMID 40636317, 2025). "Splenic expression of Lamp2 but not Lamp1 was increased after experimental stroke and analysis of mRNA levels by RT-qPCR confirmed significant upregulation of Lamp2 2 days after experimental stroke in comparison to sham surgery." (PMID 29872438, 2018).
amyloid (8 papers, 2020 to 2025). "LAMP1 involvement in amyloid pathology has been widely acknowledged, found in reactive microglial cells in senile plaques rather than diffuse deposits, suggesting an involvement in amyloid removal." (PMID 39070643, 2024). "To assess whether APOE4 reduction provides neuroprotection to plaque- and CAA-associated neural processes, we assessed neuritic dystrophy by labeling for LAMP1, a lysosomal marker that is highly enriched in large, swollen axons surrounding amyloid and CAA." (PMID 36922879, 2023). "Examining the effect of the small molecule on BACE1 and LAMP1 accumulation in dystrophic axons as well as on amyloid plaque pathology could shed more light on the contribution of these pathways to AD pathogenesis and the therapeutic potential of manipulating AP-4-dependent pathways in AD treatment." (PMID 39632089, 2024). "We speculated that lysosomal exocytosis in response to elevated calcium (Ca2+) levels during amyloid plaque growth could lead to a selective reduction in SAP- and LAMP1-labelled DNs in older AD mouse brains." (PMID 34215298, 2021). "Intriguingly, our study also revealed that immunohistochemically-detectable LAMP1 near mature amyloid plaques appeared to be in DAM, rather than in DNs." (PMID 34215298, 2021).
Parkinson disease (8 papers, 2010 to 2025). A progressive degenerative disorder of the central nervous system characterized by loss of dopamine producing neurons in the substantia nigra and the presence of Lewy bodies in the substantia nigra and locus coeruleus. "On western blotting LAMP1 levels rose significantly in controls, Gaucher disease and Parkinson’s disease with GBA mutation after ambroxol treatment (median increase 100% in each group, P < 0.05)." (PMID 24574503, 2014). "Furthermore, the loss of Lamp1 exacerbates locomotor deficits induced by the expression of the Parkinson’s-related mutant α-synuclein A30P in dopaminergic neurons, highlighting its vital role in neuroprotection." (PMID 40143028, 2025). "One recent study has found that lysosomal protease Cathepsin D, Lysosome Associated Membrane Protein 1 (LAMP1), and Heat Shock Protein 73 (HSP73) immunoreactivities are significantly decreased (each protein to about 50%) in Parkinson's disease substantia nigra neurons." (PMID 20388210, 2010). "Two studies reported that TUDCA decreased autophagy and protein levels of LAMP1 in both TGF- β1 treated fibroblasts and in a mouse model of Parkinson’s Disease." (PMID 35862710, 2022).
gastric cancer (7 papers, 2021 to 2025). A primary or metastatic malignant neoplasm involving the stomach. "Mining the Kaplan‐Meier Plotter database revealed that up‐regulation of MCOLN1 (P = 4.6 × 10−2 and 4.4 × 10−2), RAB3A (P = 7.4 × 10−7 and 5.5 × 10−6), or LAMP1 (P = 3.2 × 10−3 and 2.3 × 10−2) was associated with poor overall or event‐free survival in gastric cancer patients." (PMID 40995693, 2025). "Similarly, capping actin protein of muscle Z-line alpha subunit 1 (CAPZA1) negatively regulated the formation of autolysomes by inhibiting the expression of lysosomal-associated membrane protein 1 (LAMP1), thus inhibiting CagA-degraded autophagy and promoting the development of gastric cancer." (PMID 34195260, 2021). "Moreover, glycyrrhizin showed co-localization of both LC3B and LAMP1 in H. pylori-infected gastric cancer cells." (PMID 37038107, 2023). "Although the concept that gastric cancer cell-derived exosomes promote tumor growth and proliferation in an autocrine manner is not new, to our knowledge, this is the first microscopy study to have actually showed morphological evidence of the cross-membrane passage of LAMP1-positive vesicles." (PMID 35203558, 2022).
dengue (6 papers, 2012 to 2022). "The dengue-2 DNA vaccine uses the prM and E genes of a low-passage Philippine strain with E’s C-terminal transmembrane and cytoplasmic domains replaced by lysosome-associated membrane protein 1 (LAMP-1)." (PMID 36423035, 2022).
diabetes (6 papers, 2017 to 2025). "Diabetes-induced lysosome-associated membrane glycoprotein 1 (LAMP1) expression was predominantly increased by Drp1 deletion." (PMID 33953167, 2021). "We propose that, in addition to enhanced trafficking and secretion through the regulated secretory pathway, the hyperglucagonemia of diabetes may also be due to re-routing of glucagon from the degradative Lamp2A+ lysosome toward the secretory Lamp1+ lysosome." (PMID 34923907, 2022). "Finally, to directly address whether MOR was lysosomally degraded during diabetes, DRG were co-stained with anti-MOR antibody and lysosomal marker, Lamp-1." (PMID 33462216, 2021).
HCMV infection (6 papers, 2017 to 2025). "However, co-localization (yellow) of LAMP-1 and IgG was more prominent in HCMV-infected HMEC-1 cells, suggesting that HCMV infection promotes lysosomal trafficking of IgG." (PMID 31289263, 2019).
Salmonella Infections (6 papers, 2008 to 2024). Infections with bacteria of the genus SALMONELLA. "Experiments performed in EBSS conditions to enhance ELs perinuclear concentration, revealed that Salmonella infection fully prevents LAMP1 clustering presumably by recruiting RUFY3 to the SCV." (PMID 37463962, 2023). "Our analysis also showed similar kinetics of LAMP1 acquisition in THP1 cells following Salmonella infection." (PMID 29538403, 2018). "In order to determine the relative importance of LAMP-1 and LAMP-2 to Salmonella infection, we used RNAi to knockdown levels of these proteins in cells." (PMID 18958159, 2008). "To further demonstrate this upregulation of LAMP1 and LC3 by LPS and Salmonella infection, we used shRNA to silence the expression of TFEB in the Caco 2 cells and then treated these engineered cells with LPS or Salmonella infection." (PMID 38711975, 2024). "After Salmonella infection, SISTs (SCAMP3 tubules with no detectable LAMP1-HcRed), SIFs containing EGFP-SCAMP3 and SIFs with little EGFP-SCAMP3 were observed within the same cell." (PMID 19438519, 2009).
breast tumor (5 papers, 2018 to 2024). "The overexpression of LAMP1 has been linked to high-grade breast tumors capable of metastasis; hence, its high expression appears to be associated with malignant attributes." (PMID 32993062, 2020).
Cognitive impairment (5 papers, 2021 to 2025). Abnormal cognition is characterized by deficits in thinking, reasoning, or remembering. "CSFR1 inhibition improves long-term cognitive impairment and inflammatory response, decreases C5aR and LAMP-1, and increases synapsin-1." (PMID 35955439, 2022). "Dystrophic neurites contain high levels of LAMP1 and BACE1, and significantly contribute to extracellular plaque deposition and axonal dystrophy, resulting in synaptic loss, neurodegeneration, and cognitive deficits." (PMID 35987691, 2022). "Additionally, we observed elevated lysosomal-associated membrane protein 1 (LAMP1) and reduced levels of filamin A and RAB7 (a member of the RAS oncogene family) in the pre-AD mild cognitive impairment group." (PMID 40772191, 2025).
liver cancer (5 papers, 2015 to 2025). An epithelial or non-epithelial malignant neoplasm that arises from the liver. "This combination treatment also further induced a high expression of LC3 and LAMP1 colocalization in liver cancer cell lines." (PMID 39519229, 2024). "In the present study, we found that the combination treatment of Cabozantinib and IL-32γ overexpression further increased the number of LC3 puncta and colocalization with LC3 and LAMP1 in liver cancer cell lines." (PMID 39519229, 2024).
metastatic melanoma (5 papers, 2020 to 2024). A melanoma that has spread from its primary site to another anatomic site. "In metastatic melanoma cells A2058, indirect immunofluorescence staining has revealed clustering of LAMP molecules at the cell periphery, suggesting potential involvement of LAMP1 in cell adhesion." (PMID 39669571, 2024).